PTGES3 (prostaglandin E synthase 3)
Description:
Cytosolic prostaglandin synthase that catalyzes the oxidoreduction of prostaglandin endoperoxide H2 (PGH2) to prostaglandin E2 (PGE2). Molecular chaperone that localizes to genomic response elements in a hormone-dependent manner and disrupts receptor-mediated transcriptional activation, by promoting disassembly of transcriptional regulatory complexes. Facilitates HIF alpha proteins hydroxylation via interaction with EGLN1/PHD2, leading to recruit EGLN1/PHD2 to the HSP90 pathway.
Synonyms: cPGES; P23; TEBP
Tractability: Small molecule: a structure with a bound ligand is known. PROTAC: UniProt records ubiquitination sites on it; ubiquitination databases record sites on it; its protein half-life has been measured.
Target class: Isomerase; Enzyme
Gene: Protein-coding gene on chromosome 12 (56,663,338 to 56,688,408, reverse strand). Ensembl gene ENSG00000110958.
Subcellular location: Cytoplasm
Subcellular location (Human Protein Atlas): Cytosol; Nucleoplasm
Pathways (Reactome):
Cellular responses to stimuli: Attenuation phase; HSF1 activation; HSP90 chaperone cycle for steroid hormone receptors (SHR) in the presence of ligand
Metabolism: Aryl hydrocarbon receptor signalling; Synthesis of Prostaglandins (PG) and Thromboxanes (TX)
Signal Transduction: ESR-mediated signaling; Estrogen-dependent gene expression
Disease: Potential therapeutics for SARS
Gene Ontology:
Molecular function: DNA polymerase binding; Hsp90 protein binding; prostaglandin-E synthase activity; protein binding; telomerase activity
Biological process: chaperone-mediated protein complex assembly; positive regulation of telomere maintenance via telomerase; prostaglandin biosynthetic process; protein folding; protein stabilization; telomerase holoenzyme complex assembly; telomere maintenance via telomerase; prostanoid biosynthetic process; signal transduction; telomere maintenance; cyclooxygenase pathway
Cellular component: nucleus; protein folding chaperone complex; protein-containing complex; telomerase holoenzyme complex; chromosome, telomeric region; cytoplasm; cytosol; nucleoplasm
Genetic constraint (gnomAD): Loss-of-function variants: 3 observed, 8.93 expected, observed/expected ratio (o/e) 0.34, 90% interval 0.15 to 0.87. That is too few expected variants to judge how well the gene tolerates losing a copy. Missense variants: 57 observed, 74.49 expected, observed/expected ratio (o/e) 0.77, 90% interval 0.62 to 0.95. Synonymous variants: 22 observed, 23.29 expected, observed/expected ratio (o/e) 0.94, 90% interval 0.67 to 1.35.
Homologues: Orthologues: pig PTGES3 (100% identical), guinea pig PTGES3 (99% identical), mouse Ptges3 (99% identical), rat Ptges3 (98% identical), tropical clawed frog ptges3 (87% identical), zebrafish ptges3a (78% identical), zebrafish ptges3b (78% identical), Caenorhabditis elegans daf-41 (31% identical), Drosophila melanogaster p23 (29% identical). Paralogues in human: PTGES3L (41% identical).
Diseases named in the same sentence as PTGES3 in open-access papers:
PTGES3 is named in the same sentence as 45 diseases in open-access papers, as found by Europe PMC text mining. Sharing a sentence is not in itself a finding about the gene and the disease. The quoted sentences say what the papers report.
hepatocellular carcinoma (3 papers, 2017 to 2026). A malignant tumor that arises from hepatocytes. "In order to further explore the function of PTGES3 in the progression of HCC, we analyzed the association between PTGES3 expression and clinical phenotypes in hepatocellular carcinoma samples from TCGA." (PMID 37274225, 2023). "Our study demonstrated that PTGES3 had an essential role in a wide range of cancers, indicating the prognostic potential of PTGES3 in hepatocellular carcinoma." (PMID 37274225, 2023). "The protein expression level of PTGES3 was observed in HCC and paired normal tissues using immunohistochemistry, and our results demonstrated a higher protein expression level of PTGES3 in hepatocellular carcinoma tissues." (PMID 37274225, 2023). "High PTGES3 expression was related to the infiltration of Th2 subsets of CD4+ T cells and immune checkpoint-related genes in most cancers, especially in hepatocellular carcinoma (HCC)." (PMID 37274225, 2023).
lung adenocarcinoma (3 papers, 2022 to 2024). A carcinoma that arises from the lung and is characterized by the presence of malignant glandular epithelial cells. "In lung adenocarcinoma, PTGES3 is also an independent poor prognostic biomarker, and a high PTGES3 expression level is associated with immune invasion in cancer cells." (PMID 38245717, 2024). "PTGES3 correlates with poor patient prognosis and immune infiltrates in lung adenocarcinoma and is an oncogenic driver within a 10-gene metabolic panel in NSCLC." (PMID 36551208, 2022). "However, the clinical outcome and immune regulation of PTGES3 in lung adenocarcinoma (LUAD) are not fully understood." (PMID 37416927, 2023).
prostate carcinoma (3 papers, 2023 to 2025). A carcinoma that arises from epithelial cells of the prostate gland. "Genome-wide CRISPRi screens for modulators of androgen receptor (AR) protein levels using live-cell quantitative endogenous AR fluorescence reporters identify PTGES3 as a new regulator of AR stability and function in prostate cancer." (PMID 41193657, 2025). "In recent years, there has been an increasing interest in the tumorigenic role of PTGES3 in multiple cancer types, including colorectal cancer, prostate cancer, and acute lymphoblastic leukemia." (PMID 37416927, 2023). "In prostate cancer, PTGES3 was reported to induce the androgen receptor activity and chromatin binding to promote tumorigenesis." (PMID 37416927, 2023). "Furthermore, analysis of the TCGA PRAD cohort revealed a significant correlation between expression of FUT8 and genes for IGFBP5, IL1B and PTGES3 in clinical prostate cancer tissue." (PMID 40387385, 2025).
cervical cancer (2 papers, 2023 to 2024). A primary or metastatic malignant neoplasm involving the cervix. "In addition, it was revealed that PTGES3 was negatively associated with immunoinhibitors, immunostimulators, and Major Histocompatibility Complex molecules in cervical cancer." (PMID 37416927, 2023). "In breast and cervical cancers, E2 was found to upregulate the expression of PTGES3, potentially promoting an immunosuppressive environment." (PMID 39598420, 2024).
colorectal cancer (2 papers, 2019 to 2023). A primary or metastatic malignant neoplasm that affects the colon or rectum. "A study reported that PTGES3 is overexpressed in tumor tissues and underexpressed in the adjacent mucosa, in colorectal cancer." (PMID 37416927, 2023). "The strong down-regulation of prostaglandin E synthase 3, validated by PRM, also suggest a significant role of the prostaglandin synthesis in the anticancer activity of DHA-MAG in these colorectal cancer cells." (PMID 31817645, 2019).
hypothyroidism (2 papers, 2021 to 2024). Abnormally low levels of thyroid hormone. "This suggests that hypothyroidism may stimulate the synthesis of PTGES2 and inhibit the synthesis of PGFS but does not affect the synthesis of PTGES-3 or PGIS." (PMID 34573602, 2021).
pancreatic cancer (2 papers, 2023 to 2025). "In another study utilizing single-cell sequencing data of pancreatic cancer, PTGES3 expression was prominently seen in multiple immune cells, whereas PTGES expression was mostly confined to fibroblast and tumor cells." (PMID 37108468, 2023).
acute respiratory distress syndrome (1 paper, 2023). Progressive and life-threatening pulmonary distress in the absence of an underlying pulmonary condition, usually following major trauma or surgery. "As the co-chaperone of HSP90, PTGES3 (P23) has been found can activate the RIPK3/MLKL during the necroptosis in acute respiratory distress syndrome." (PMID 38020922, 2023).
adenoma (1 paper, 2023). A neoplasm arising from the epithelium. "In contrast, PTGS1 (COX-1) and PTGES3 (cPGES) were expressed at higher levels suggesting an important contribution to colorectal tissue PGE2 biosynthesis; their expression levels were comparable in adenomas and normal colorectal mucosa." (PMID 37173923, 2023).
cholangiocarcinoma (1 paper, 2023). A carcinoma that arises from the intrahepatic biliary tree (intrahepatic cholangiocarcinoma) or from the junction, or adjacent to the junction, of the right and left hepatic ducts (hilar cholangiocarcinoma). "In addition, PTGES3 was found to be a hub gene enriched in cell cycle-related pathways in cholangiocarcinoma (CCA), which could serve as a prognostic marker." (PMID 37416927, 2023).
cognitive decline (1 paper, 2025). "Some of these genes are also involved in aging, and prostaglandin E synthase (PTGES3), an enzyme involved in prostaglandin‐2 synthesis, has been shown to be upregulated in aging‐induced cognitive decline." (PMID 39380362, 2025).
COVID-19 (1 paper, 2021). A disease caused by infection with severe acute respiratory syndrome coronavirus 2. "PTGES3 encodes for the prostaglandin E synthase 3, a protein that synthesizes prostaglandin E2 from prostaglandin endoperoxide H2, and it is downregulated in AD+COVID-19." (PMID 34948400, 2021).
dyspepsia (1 paper, 2023). An uncomfortable, often painful feeling in the stomach, resulting from impaired digestion. "Previous studies have revealed that PTGES3 participates in the regulation of various diseases, including pediatric recurrent abdominal pain, oscillatory shear stress, dyspepsia, and cancers." (PMID 37416927, 2023).
endometrial adenocarcinomas (1 paper, 2011). "Here we investigated (a) the expression profile of the PGE synthase enzymes (PTGES, PTGES-2, PTGES-3) and PGE receptors (PTGER1–4) in endometrial adenocarcinomas compared with normal endometrium and (b) the role of PTGER4 in endometrial tumorigenesis in vivo." (PMID 21589857, 2011).
leukemia (1 paper, 2023). A malignant (clonal) hematologic disorder, involving hematopoietic stem cells and characterized by the presence of primitive or atypical myeloid or lymphoid cells in the bone marrow and the blood. "It has been demonstrated that leukemia cells with PTGES3 knockdown had an elevated therapeutic response in bone marrow." (PMID 37274225, 2023).
nephrosclerosis (1 paper, 2023). Hardening of the kidney due to infiltration by fibrous connective tissue (fibrosis), usually caused by renovascular diseases or chronic hypertension. "The addition of three variants, namely PTGS2 rs4648268, PTGES3 rs2958155 and PTGES3 rs11300958, to a predictive model for CV events containing classic risk factors in nephrosclerosis patients, significantly enhanced its statistical power (AUC value increased from 78.6 to 87.4%, p = 0.0003)." (PMID 36690661, 2023). "We aimed to determine whether genetic variability represented by 38 tag-SNPs in genes of the cyclooxygenase pathway (PTGS1, PTGS2, PTGES, PTGES2 and PTGES3) leading to prostaglandin E2 (PGE2) synthesis, modified CV traits and events in 493 nephrosclerosis patients." (PMID 36690661, 2023).
opioid dependence (1 paper, 2019). "Heat shock proteins are known to be differentially expressed in opioid dependence and withdrawal but the functional significance of low Ptges3 expression is unknown." (PMID 31333398, 2019).
thyroid carcinoma (1 paper, 2023). "In contrast, PTGES3 expression was lower in kidney chromophobe (KICH), thyroid carcinoma (THCA), and uterine corpus endometrial carcinoma (UCEC) compared to the normal tissues." (PMID 37416927, 2023).
tumor (23 papers, 2009 to 2026). "Single-cell RNA sequencing (scRNA-seq) and histological analysis reveal that PTGES3 deficiency remodels the immune landscape, specifically by impairing tumor-associated macrophage (TAM) infiltration and M2 polarization." (PMID 41880053, 2026). "PTGES3 expression was also associated with the abundance of immune cell infiltration, the response to ICIs, and multiple pathways related to tumor progression in HCC." (PMID 37274225, 2023). "The CPTAC data further demonstrated that PTGES3 expression level was significantly associated with cancer stage (P < 0.05, stage 1 vs. stage 3) and tumor grade (P < 0.001, grade 2 vs. grade 3)." (PMID 37416927, 2023). "Additionally, we found the overexpression of PTGES3 was positively associated with cancer stage and tumor grade in LUAD." (PMID 37416927, 2023). "Here, we identify PTGES3 as a dual-function regulator coupling tumor intrinsic growth with extrinsic immune remodeling." (PMID 41880053, 2026). "We observed that repression of PTGES3 significantly delayed tumor growth in vivo relative to controls." (PMID 41193657, 2025). "We measured PTGES3 localization by immunohistochemistry (IHC) using a validated PTGES3 antibody on a tissue microarray containing 120 PCa tumor biopsies." (PMID 41193657, 2025). "Low expression of PTGES3 in metastatic tumor cells leads to excessive activation of glucose oxidation, ultimately facilitating tumor cell entry into the hepatic parenchyma." (PMID 40027151, 2025). "At tumor onset we administered doxycycline to the mice to induce PTGES3 repression and tracked tumor size over time." (PMID 41193657, 2025). "In conclusion, PTGES3 expression in tumor was statistically higher than normal tissues both at the transcriptional and protein levels, which was also linked to their prognosis." (PMID 37274225, 2023). "Firstly, gene and protein expression of PTGES3 were analyzed using Tumor Immune Estimation Resource (TIMER), R software, Clinical Proteomic Tumor Analysis Consortium (CPTAC), and Human Protein Atlas (HPA)." (PMID 37416927, 2023). "The strong correlation between PTGES3 and these different immune cell types suggests that PTGES3 affected the polarization of Th2 and macrophage cells, which, in turn, promoted the tumor development." (PMID 37274225, 2023). "Another research also reported that AIL inhibited tumor growth in GC cells through downregulating the DNA repair activity of malignant cells, which suggest that PTGES3 has the potential as a therapy target in novel treatments." (PMID 37274225, 2023). "Our research demonstrated theprognostic predictive value of PTGES3 in a wide range of cancers, which was alsoassociated with the process of tumor immune infiltration." (PMID 37274225, 2023). "The results of TIMER analysis demonstrated a correlation between PTGES3 expression and clinical features such as tumor stage and age, which was significantly different in LIHC, KIRP, LUSC, and BRCA-lumb." (PMID 37274225, 2023). "Subsequently, we collected the clinical data from these samples and explored the correlation between the PTGES3 protein expression level and clinical characteristics, from which we only found that PTGES3 expression correlated with the pathological tumor stage." (PMID 37274225, 2023). "The gene and protein expression of PTGES3 were elevated in LUAD tissues and compared to the normal tissues, and the high expression of PTGES3 was correlated with cancer stage and tumor grade." (PMID 37416927, 2023). "PTGES3 helps Hsp90 with protein folding and stabilizing in a wide range of proteins, which is proven to be involved in various biological processes and tumor pathogenesis." (PMID 37274225, 2023). "RNA-Seq of the primary tumor identified four fusion genes, PTGES3-PTPRB, HMGA2-DYRK2, TMBIM4-MSRB3 and USP15-CNTN1, in which all the partner genes map to the q arm of chromosome 12." (PMID 25176350, 2014).
tumor (continued). "RT-PCR using cDNA from the primary tumor and subsequent direct Sanger sequencing verified the presence of PTGES3-PTPRB, HMGA2-DYRK2, TMBIM4-MSRB3 and USP15-CNTN1 chimeric transcripts." (PMID 25176350, 2014). "Furthermore, higher tumor expression of PTGES3 was correlated with worse overall survival in mCRPC patients treated with a first-line AR-targeted therapy (abiraterone, enzalutamide or apalutamide)." (PMID 41193657, 2025). "Since PTGES3 expression had an association with TMB and MSI that affects the sensitivity of immunotherapy in multiple types of tumors, we explored the influence of PTGES3 expression on the abundance of tumor cell infiltrates." (PMID 37274225, 2023). "Additionally, it revealed that mRNA and protein expression of PTGES3 were significantly upregulated in LUAD and that its high expression was associated with cancer stage and tumor grade." (PMID 37416927, 2023). "The role played by PTGES3 in the DSS of tumor patients was observed for further evaluation." (PMID 37274225, 2023). "Furthermore, we investigated the potential genetic alteration of PTGES3 in various cancer types, which included copy number variation (CNV), DNA methylation, tumor mutational burden (TMB), and microsatellite instability (MSI)." (PMID 37274225, 2023). "The TIMER tool was used to assess the differential expression of PTGES3 in diverse tumor tissues." (PMID 37416927, 2023). "The results showed that all prognostic CRGs were elevated in advanced LUAD samples as well as in LUAD samples with brain metastases; in particular, EGFR was more expressed in samples with brain metastases, while PTGES3 was significantly elevated in all tumor samples used." (PMID 36060936, 2022). "According to the results of Gene Ontology (GO) analysis, several SNO proteins, such as glutamate dehydrogenase 1 (GLUD1), pyruvate kinase PKM (PKM), and prostaglandin E synthase 3 (PTGES3), might be involved in the metabolic pathways that are important in tumor endocrine biological processes." (PMID 37124724, 2023). "Our results showed that PTGES3 expression was correlated with 12 types of tumor in TMB and 10 types of tumor in MSI." (PMID 37274225, 2023). "Lastly, the role of PTGES3 in immune regulation in LUAD was investigated using TIMER, Tumor-Immune System Interaction Database (TISIDB), and SangerBox." (PMID 37416927, 2023). "The results in TIMER2.0 indicated that PTGES3 expression levels significantly correlated with clinical phenotypes of patients in BRCA, KIRP, LIHC, LUAD, and PRAD, which included tumor stage, race, gender, and age." (PMID 37274225, 2023). "Prostaglandin E synthase enzyme 3 (PTGES3), also known as p23, is an oncogene mediating the expression of prostaglandin E2 (PGE2), which promotes tumor growth through multifactorial mechanisms such as upregulating anti-apoptotic genes." (PMID 37274225, 2023). "ADH5, NUDT7, PTGES3, D2HGDH, HAO2 and CPT1C also play regulatory roles in the pathological processes of various tumours." (PMID 36643625, 2023). "The accumulation of PTGES3 and PRXL2B transcripts in tumor tissue correlates with a simultaneous reduction of oncomiRs miR-223, miR-19a, miR-605, and miR-486, miR-211, miR-423, respectively." (PMID 35453789, 2022). "The cBio Portal generated a network showing that ENO1, PTGES3, NPM1 and STMN1 are connected in this tumor." (PMID 29545914, 2018). "MDM2 amplification and the fusion transcripts PTGES3-PTPRB, HMGA2-DYRK2, TMBIM4-MSRB3 were found both in the primary tumor and the metastasis examined, showing that the same clone set up these two tumor lesions." (PMID 25176350, 2014). "Some proteins from this list have also been identified in tumor studies as clinical outcome predictors (NOV, CLU TNC, POSTN, IGFBP2, LCN2) or mediators of resistance to chemotherapy (CLU, FBLN1, THBS, STIP1, PTGES3, IGFBP4, ATOX1)." (PMID 19936259, 2009).